BRCA2 (BRCA2 DNA repair associated)
Diseases named in the same sentence as BRCA2 in open-access papers (continued):
Sharing a sentence is not in itself a finding about the gene and the disease.
ovarian carcinoma (continued). "BRCA1 or BRCA2 mutations are a high-risk factor for HGSC, and women harboring such mutations have a 30% to 70% probability of developing ovarian cancer by the age of 70." (PMID 24063014, 2013). "The lifetime risk of ovarian cancer in BRCA1 and BRCA2 mutation carriers is approximately 40–60 and 10–25%, respectively." (PMID 22388872, 2012). "PARP inhibitors have demonstrated promising results in patients with BRCA1- or BRCA2-positive ovarian cancer." (PMID 22253870, 2012). "Several common alleles have been shown to be associated with breast and/or ovarian cancer risk for BRCA1 and BRCA2 mutation carriers." (PMID 22348646, 2012). "In the period between January 2009 and December 2011, 559 individuals from 379 families affected with breast and/or ovarian cancer were screened for mutations in the BRCA1 and BRCA2 genes." (PMID 22923021, 2012). "Approximately 5% to 10% of hereditary breast and ovarian cancers result from dominant mutations in known single genes, particularly BRCA1/BRCA2." (PMID 22314128, 2012). "Additionally, screening for germline mutations in BRCA1/BRCA2 is also a promising method for early detection of ovarian cancer in current clinical practice since high risk populations with corresponding mutations could be genetically predisposed toward developing cancer." (PMID 23319948, 2012). "Meta-analyses have revealed a wide variance in cumulative ovarian cancer risk for BRCA mutation carriers, on average 40% in BRCA1 versus 11-18% in BRCA2 mutation carriers." (PMID 23039163, 2012). "A previous study performed by our group found 12.8% of clinically high-risk Chinese probands with breast and/or ovarian cancers carried a deleterious BRCA mutation, of which 60.7% were BRCA2 mutations." (PMID 22290208, 2012). "Ovarian cancers are associated with breast cancer 1 (BRCA1) and BRCA2 oncogenes, variously inherited as germline mutations." (PMID 22481932, 2012). "Here we report the distribution of the MDM2 SNP285G>C and SNP309T>G polymorphisms in 221 Norwegian ovarian cancer patients diagnosed with germline mutations in BRCA1 (n = 161) and BRCA2 (n = 60)." (PMID 23039163, 2012). "The identification of the two major hereditary breast/ovarian cancer genes, BRCA1 (17q21, MIM* 113705) in 1994 and BRCA2 (13q14, MIM* 600185) in 1995, led to a new era in the diagnosis of inherited high predisposition to breast and ovarian cancer." (PMID 23961350, 2012). "We describe here the results of BRCA1/BRCA2 germline analysis in an Argentinean series of breast/ovarian cancer patients selected for young age at diagnosis or breast/ovarian cancer family history." (PMID 23961350, 2012). "Germline mutations in BRCA1 and BRCA2 confer higher risk of ovarian cancer; the estimated risk for BRCA1 mutation carriers range between 16% and 68% by age 70 and between 11% and 27% for BRCA2 mutation carriers." (PMID 23319948, 2012). "Women with a known BRCA1 or BRCA2 mutation should be offered prophylactic mastectomy and bilateral salpingo-oophorectomy (BSO) in order to decrease the risk of breast and ovarian cancer." (PMID 22312502, 2011). "About 5-10% of breast and ovarian carcinomas are hereditary and most of these result from germline mutations in the BRCA1 and BRCA2 genes." (PMID 22185575, 2011). "The role of BRCA1 and BRCA2 in the pathogenesis of breast and ovarian cancer in Pakistan was noted, and the most prevalent Pakistani mutations were highlighted." (PMID 21559243, 2011). "The c.68-7T>A variant, initially described in one patient with breast and ovarian cancer in Italy, has been widely detected in France (82 times, UMD-BRCA2 database) sometimes with co-occurrence of two different deleterious BRCA2 mutations." (PMID 21939546, 2011). "EMSY interacts directly with BRCA2 and links the BRCA2 pathway to sporadic breast and ovarian cancer." (PMID 21056705, 2011). "The reported cumulative risk for ovarian cancer in BRCA1 and BRCA2 carriers at the age of 70 was 39% to 60% and 22% to 27%, respectively." (PMID 21232165, 2011).
ovarian carcinoma (continued). "Even more significant, among Jewish woman with ovarian cancer, there is an estimated 29% risk of carrying a BRCA1 or BRCA2 mutation." (PMID 22312502, 2011). "The abnormalities of FANCD1/BRCA2 gene have been reported in other cancer cells such as breast or ovarian cancer cells." (PMID 21573016, 2011). "Women at high ovarian cancer risk, especially those with mutations in BRCA1/BRCA2, are encouraged to undergo bilateral risk-reducing salpingo-oophorectomy (BRRSPO) prior to the natural menopause." (PMID 21654687, 2011). "For example the mouse tumors expressed higher levels of BRCA2,a known tumor suppressor gene in breast and ovarian cancer and involved inmaintenance of genome stability, specifically the homologous recombination pathwayfor double-strand DNA repair." (PMID 21559450, 2011). "Germline mutations in either of the two tumor-suppressor genes, BRCA1 and BRCA2, account for a significant proportion of hereditary breast and ovarian cancer cases." (PMID 21989022, 2011). "The risk of ovarian cancer by age 70 in BRCA1 mutation carriers is between 39–63%, and 11–30% for BRCA2 carriers." (PMID 21654687, 2011). "The lifetime risk of ovarian cancer is 45–60% for BRCA1-mutation carriers and 11–35% for BRCA2-mutation carriers." (PMID 22312502, 2011). "Specifically, ovarian cancers frequently exhibit “BRCAness” due to defects in BRCA1 or BRCA2, or other ill-defined changes that disrupt the homologous recombination DNA repair pathway." (PMID 22194930, 2011). "EMSY was discovered in a screen for BRCA2 interactors and it links the BRCA2 pathway to sporadic breast and ovarian cancer." (PMID 21056705, 2011). "Approximately 8–15% of ovarian cancers are thought to be caused by inheritance of germline mutations in high-risk cancer-predisposing genes, such as BRCA1 and BRCA2." (PMID 21654687, 2011). "The lifetime risk of ovarian cancer for BRCA1 and BRCA2 mutation carriers is estimated at 40–50% and 10–20%, respectively." (PMID 20069122, 2010). "The 16 familial case patients who had breast or ovarian cancer and at least one relative with these cancers were analyzed for mutations in the BRCA1 and BRCA2 genes." (PMID 20380699, 2010). "We have suggested that all incident cases of breast or ovarian cancer in Norway should be offered testing for the Norwegian deleterious BRCA1 and BRCA2 mutations." (PMID 20180971, 2010). "These mutations increase the risk for developing ovarian cancer by 26% (BRCA1) and 10% (BRCA2) during a woman's life time." (PMID 23554638, 2010). "The ovarian cancer risk for BRCA1 and BRCA2 mutation carriers was 40% (95% CI, 35% - 46%) and 18% (95% CI, 13% - 23%) respectively." (PMID 19825178, 2009). "In a 2003 report the risk of breast and ovarian cancer for Ashkenazi women with inherited mutations in the tumor suppressor genes BRCA1 and BRCA2 has been estimated." (PMID 19825178, 2009). "In this study BRCA1, BRCA2 and CHEK2*(1100delC) were analyzed for mutations in 91 HBOC/HBC/HOC families and early onset breast and early onset ovarian cancer cases." (PMID 19656415, 2009). "For ovarian cancer, the known highly penetrant susceptibility genes (BRCA1 and BRCA2) are probably responsible for only 40% of the excess familial ovarian cancer risks, suggesting that other susceptibility genes of lower penetrance exist." (PMID 19543528, 2009). "Among BRCA1 and BRCA2 mutation carriers, there is considerable variability in both the age at diagnosis and the incidence of breast and ovarian cancers, even among women who carry the same BRCA1 and BRCA2 mutation." (PMID 19843326, 2009). "BRCA1 promoter methylation occurs in 5–20% of sporadic ovarian carcinomas, while BRCA2 methylation is rare." (PMID 19602291, 2009). "The most advanced case is the PARP-1 inhibitors, on their own or in combination with DNA-damaging chemotherapeutics, which are in phase-II clinical trials with breast/ovarian cancer patients having BRCA1/BRCA2 null tumours." (PMID 19319136, 2009).
ovarian carcinoma (continued). "In the same study, the lifetime risk of ovarian cancer was 54% for BRCA1 and 23% for BRCA2 mutation carriers." (PMID 19825178, 2009). "Our data demonstrate that BRCA1 and BRCA2 protein expression are highly concordant in ovarian carcinomas." (PMID 19602291, 2009). "Germline mutations in the BRCA1 and BRCA2 (BRCA1/2) tumor suppressor genes are highly penetrant for increased risks of breast and ovarian cancers." (PMID 19277124, 2009). "Most studies report improved survival in women with ovarian carcinomas associated with BRCA1 and BRCA2 mutations compared to women with sporadic ovarian carcinoma, consistent with increased sensitivity to platinum-based chemotherapy." (PMID 19602291, 2009). "For ovarian cancer the risk is 39% and 11%, in BRCA1 and BRCA2 mutation carriers by 70 years, respectively." (PMID 19656415, 2009). "A recent case-control study included 779 jewish women affected by hereditary ovarian cancer who had undergone genetic testing for three Askhenazi founder mutations (BRCA1 185delAG, 5382insC; BRCA2 617delT)." (PMID 19825178, 2009). "Downstream proteins such as FANCD1/BRCA2, FANCJ/BRIP1 and FANCN/PALB2 have been linked to elevated risk of breast and ovarian cancers." (PMID 20043851, 2009). "As part of the model-fitting process, we also estimated the BRCA1 and BRCA2 breast and ovarian cancer risks, but these were based on a relatively small number of mutation-carrying families and were therefore imprecise." (PMID 18349832, 2008). "Mutations in BRCA1 (breast cancer 1, early onset; MIM#113705) and BRCA2 (Breast Cancer Type 2 susceptibility protein; MIM#600185) account for an autosomal dominant transmission of susceptibility to breast and ovarian cancer." (PMID 18489799, 2008). "The penetrance of ovarian cancer is much lower in IVS16-2A>G BRCA2 families than in BRCA1 families with a Ring domain missense mutation or the 1806C>T mutation." (PMID 18783588, 2008). "This is the first study to comprehensively examine data from detailed analysis of BRCA1 and BRCA2 abnormalities in ovarian cancer." (PMID 18208621, 2008). "AA504130 is located on 13q12.3, similarly to BRCA2, which is known as a marker of breast and ovarian cancer." (PMID 18554423, 2008). "There is still uncertainty as to why BRCA2 families, ascertained on the basis of members with breast and/or ovarian cancer, have a higher RR of prostate cancer in men carrying protein-truncating BRCA2 mutation." (PMID 17700570, 2007). "FA proteins are closely related to the breast/ovarian cancer susceptibility genes products BRCA1 and BRCA2, and to their partner proteins." (PMID 18047734, 2007). "BRCA1/2 mutation carriers have a high lifetime risk of developing ovarian cancer (39% for BRCA1, 11–22% for BRCA2 at age 70 years)." (PMID 17426707, 2007). "A few hundred different mutations associated with inherited predisposition to breast and ovarian cancers have been identified in the BRCA1 and BRCA2 genes, as described at the Breast Cancer Information Core internet web site (BIC database)." (PMID 17561994, 2007). "Breast and ovarian cancer risk in BRCA1 and BRCA2 carriers is a complex trait, affected by genetic modifiers and nongenetic factors." (PMID 17213823, 2007). "Discussing all published studies of breast and ovarian cancer risk in BRCA1 and BRCA2 carriers is beyond the scope of this review, but we would like to address the variability of risk estimates in the literature." (PMID 17213823, 2007).
ovarian carcinoma (continued). "At the first screening visit, five women (four BRCA1 and one BRCA2) were diagnosed with a prevalent ovarian cancer." (PMID 17426707, 2007). "BRCA1 and BRCA2 proteins are thought to be essential to prevent breast/ovarian cancer largely because of the high lifetime risks faced by carriers of mutations in the corresponding genes." (PMID 17683622, 2007). "In the present study we used data from French-Canadian families included in the INHERIT program to evaluate the mutation risk prediction models BOADICEA and BRCAPRO and to estimate the breast and ovarian cancer risks conferred by BRCA1 and BRCA2 mutations." (PMID 16417652, 2006). "We also used this data set to estimate the risks for breast and ovarian cancer conferred by BRCA1 and BRCA2 mutations." (PMID 16417652, 2006). "The lifetime risk of carriers for developing ovarian cancer is high, 35–60% for BRCA-1 mutation carriers and 10–20% for BRCA-2 mutation carriers, in contrast to the 1.8% lifetime risk of the general population." (PMID 16495917, 2006). "The estimated risks for breast and ovarian cancer in BRCA1 and BRCA2 mutation carriers were consistent with previously published estimates." (PMID 16417652, 2006). "In the present study we estimated breast and ovarian cancer risks conferred by BRCA1 and BRCA2 mutations in French-Canadian families." (PMID 16417652, 2006). "We also used this data set to estimate the age-specific risks for breast and ovarian cancer in BRCA1 and BRCA2 mutation carriers." (PMID 16417652, 2006). "The year 2003 brought the first direct-to-consumer advertising for an inherited breast and ovarian cancer susceptibility genetic test (BRCA1 and BRCA2)." (PMID 15888219, 2005). "Almost 10% of epithelial ovarian cancer cases are associated with dominant genetic predisposition, in most cases (80 – 90%), linked to mutations in BRCA1 or BRCA2." (PMID 16229746, 2005). "About 10% of ovarian cancer patients inherit a familial predisposition, and of those cases, only 35–50% can be attributed to the inheritance of defects in the BRCA1 and BRCA2 tumor suppressor genes." (PMID 15918899, 2005). "Genetic testing for the breast and ovarian cancer susceptibility genes BRCA1 and BRCA2 can help in the clinical management of individuals with family history (FH) of the disease, by identifying individuals at highest risk." (PMID 15381934, 2004). "Both OC use and tubal ligation have also shown substantial protection against ovarian cancer in BRCA1 and BRCA2 mutation carriers." (PMID 15345077, 2004). "Two of the first common cancer genes to be mapped and cloned were the breast and ovarian cancer susceptibility genes BRCA1 and BRCA2." (PMID 15138471, 2004). "The same table shows the predicted contributions of BRCA1 and BRCA2 to cases diagnosed with ovarian cancer." (PMID 15381934, 2004). "At the age of 70, the cumulative risk of developing ovarian cancer in a BRCA1 mutation carrier ranges from 16 to 85%, whereas the risk with a BRCA2 mutation is 10–27%." (PMID 15083174, 2004). "Especially, BRCA1 mutations conferred an increased risk for ovarian cancer: on average, there were nearly three times as many ovarian cancers in BRCA1 families than in BRCA2 families (0.89 vs 0.32; P=0.091)." (PMID 15026808, 2004). "It is estimated that BRCA1 and BRCA2 are responsible for 5 – 10% of breast cancer cases and 10% of ovarian cancer cases." (PMID 15138471, 2004). "BRCA1 and BRCA2 have been reported to be factors influencing survival in ovarian cancers." (PMID 41614943, 2026). "Thus, BRCA1/BRCA2’s strong tumor-suppressive effects appear largely confined to hereditary breast and ovarian cancer." (PMID 40841483, 2026).
ovarian carcinoma (continued). "HRD scores were comparable between BRCA1-and BRCA2-mutated ovarian cancer but significantly higher than in patients with non-BRCA HRR-related pathogenic mutations (P < 0.001) or wild-type HRR-related genes (P < 0.001)." (PMID 40687614, 2025). "Since the onset of ovarian cancer tends to occur later in carriers of a BRCA2 variant, RRSO for managing ovarian cancer risk in these women is recommended between the ages of 40 and 45, unless the age at diagnosis in the family warrants considering this prophylactic surgery at an earlier age." (PMID 40303993, 2025). "Ovarian cancer mortality is reduced by up to 96% if a risk-reducing salpingo-oophorectomy [RRSO] is performed before ovarian incidence rises [age 35–40 years for BRCA1 carriers and age 40–45 years for BRCA2 GPV carriers]." (PMID 40427184, 2025). "BRCA1 and BRCA2 are the most frequently mutated genes in hereditary breast and ovarian cancer syndromes; loss of BRCA1 and BRCA2 is indeed associated with a lifelong increased incidence of breast and ovarian cancer of ~80% and ~25–50%, respectively." (PMID 39927794, 2025). "Frontline PARP inhibitor maintenance therapy provides a substantial PFS benefit for newly diagnosed epithelial ovarian cancer patients with BRCA pathogenic variants, with the most pronounced efficacy observed in mutations located within the DNA-binding domains of BRCA1 and BRCA2." (PMID 40075604, 2025). "Mutations found in Australian women with a strong history of breast and ovarian cancer but not BRCA1 or BRCA2 mutation are located in the MM1 domain, and appear essential for FANCF binding." (PMID 40447800, 2025). "This study adds to previous observations regarding BRCA2 splicing in ovarian cancer." (PMID 40724944, 2025). "BRCA1- and BRCA2-associated hereditary breast and ovarian cancer (HBOC) is characterized by an increased risk for male and female BC, ovarian cancer (including fallopian tube and primary peritoneal cancers), and, to a lesser extent, other cancers, such as prostate, pancreatic, and melanoma." (PMID 40648909, 2025). "It is widely recognized in the field of synthetic lethality that molecularly targeted therapies such as PARP inhibitors possess the potential to greatly extend the progression-free and overall survival rates for individuals with BRCA1- or BRCA2-mutant ovarian cancer." (PMID 40781291, 2025). "The links between breast/ovarian cancer and BRCA2 are well supported by literature." (PMID 39799398, 2025). "BRCA2 exon 11 mutations were associated with improved PFS, which underscores the prognostic significance of the BRCA mutation location, particularly exon 11, in ovarian cancer." (PMID 40427158, 2025). "However, the clinical outcome of women carrying BRCA1 and BRCA2 P/LP variants seems to be similar to that of patients with a single BRCA1 P/LP variant, and the probability of developing breast and ovarian cancers is comparable to those with single mutations." (PMID 39858629, 2025). "In cases such as breast and ovarian cancer, the detection of BRCA1 and BRCA2 mutations facilitates targeted interventions, including chemoprevention and risk-reducing surgeries, which have proven efficacy in lowering the incidence of cancer in high-risk populations." (PMID 41541272, 2025). "In Japan, the proportion of germline variants in ovarian cancer is approximately 18%, and the major genes are BRCA1, BRCA2, mismatch repair genes [MutL protein homolog (MLH) 1, MLH2, MLH6, and postmeiotic segregation increased 2], RAD51 Paralog D, and ataxia telangiectasia mutated (ATM)." (PMID 39807103, 2025). "This suggests that MGO accumulation in ovarian cancer may serve a protective role when BRCA2 is impaired, potentially impacting BRCA2 function and influencing ovarian cancer progression through Glo1 regulation." (PMID 40191206, 2025).